CEACAM6 (CEA cell adhesion molecule 6)
Diseases named in the same sentence as CEACAM6 in open-access papers (continued):
Sharing a sentence is not in itself a finding about the gene and the disease.
breast carcinoma (continued). "CEACAM6 is increased in pancreatic adenocarcinoma, breast cancer, non small cell lung cancer, gastric cancer, colon cancer and other cancers and promotes tumor progression, invasion, and metastasis." (PMID 38633792, 2024). "CEACAM6 is an intercellular adhesion molecule that is overexpressed in a wide variety of human cancers, including breast cancer, pancreatic cancer, and lung cancer, and is associated with tumorigenesis, tumor cell adhesion, invasion, and metastasis." (PMID 36079985, 2022). "Overall, gene-based aggregation analyses revealed that rare PTVs in CEACAM6, CEACAM7, and CEACAM8 are associated with European American breast cancer risk, and rare PTVs in CEACAM7 are associated with breast cancer risk in African Americans." (PMID 34447411, 2021). "Gene-based analyses determined that rare PTVs in CEACAM6, CEACAM7, and CEACAM8 are associated with European American breast cancer risk, and rare PTVs in CEACAM7 are associated with breast cancer risk in African Americans." (PMID 34447411, 2021). "Rare PTVs in CEACAM6 and CEACAM8 appear to only be associated with European American breast cancer risk." (PMID 34447411, 2021). "Gene-based aggregation analyses revealed that rare PTVs in CEACAM6, CEACAM7, and CEACAM8 are associated with European American breast cancer risk, and rare PTVs in CEACAM7 are associated with breast cancer risk in African Americans." (PMID 34447411, 2021). "Previously, we have examined CEACAM6 and found a similar correlation to a differentiation hierarchy both in normal epithelial tissue and in breast cancer." (PMID 33196697, 2020). "Among the hubs of the 6 modules, 5 of them (PTPN22, BRIP1, CEACAM6, LTF, and CCNT1) have been previously found to be associated with breast cancer, and the other one, MXRA5, has been reported to be related to non-small cell lung cancer." (PMID 30240439, 2018). "Previous studies have shown that CEACAM6 is detected in approximately 70% of solid tumors, including breast cancer." (PMID 30240439, 2018). "We recently reported the interaction of HER2 with carcinoembryonic antigen-related cell adhesion molecule 6 (CEACAM6) in breast cancer tissues." (PMID 30326622, 2018). "In recent study, CEACAM6 was reported as predictive for endocrine therapy resistance and a unique mediator of migration and invasion of drug-resistant estrogen-deprived breast cancer cells." (PMID 25427744, 2015). "CEACAM6 was previously reported to be overexpressed in breast cancer however, the level of CEACAM6 over expression appeared modest presumably since immunohistochemistry alone was used to assess CEACAM6 expression." (PMID 23592399, 2013). "This study therefore provides a more detailed understanding of the CEACAM6 expression in breast cancer." (PMID 23592399, 2013). "This resulted in the loss of viability of tumor cells in vitro, supporting an oncogenicrole for both PDEF and CEACAM6 in breast cancer." (PMID 23592399, 2013). "The largely concordant expression of PDEF and CEACAM6 in primary breast tumors is also consistent with the notion that CEACAM6 is a PDEF induced gene in breast cancer." (PMID 23592399, 2013). "Accordingly, this communication describes CEACAM6 (carcinoembryonic antigen related cell adhesion molecule 6) as a PDEF induced molecule in breast cancer." (PMID 23592399, 2013). "This study identifies CEACAM6 as a robust predictive biomarker for neoadjuvant chemotherapy (NAC) response in hormone receptor-positive/human epidermal growth factor receptor 2-negative (HR+/HER2−) breast cancer." (PMID 40936892, 2025). "Furthermore, high CEACAM6 expression is predominantly associated with luminal and HER2‐enriched breast cancer subtypes compared to basal‐like subtypes." (PMID 40856433, 2025). "Our findings suggest that CEACAM6 may function not only as a predictor of chemotherapy response but also as a potential therapeutic target in HR+/HER2− breast cancer." (PMID 40936892, 2025).
breast carcinoma (continued). "Additionally, previous research has confirmed the roles of these five central genes (CEACAM6, CAMP, PNPLA2, OLR1, and ADIPOR1) in breast cancer, which were consistent with our predictions of risk and protective factors." (PMID 40282270, 2025). "Compared to well-established biomarkers in HR+/HER2− breast cancer, such as ESR1 mutations and PI3K/AKT pathway genes, CEACAM6 may offer complementary predictive value by capturing both chemotherapy sensitivity and immune microenvironment status." (PMID 40936892, 2025). "Third, whether LM patients derived from other solid tumors, such as breast cancer and melanoma representing most common causes of LM, showing positive CSF HE4 and CEACAM6 detection deserve our further attention." (PMID 38304432, 2024). "Currently, CEACAM6 is applied for breast-cancer-targeted treatment and diagnosis for breast cancer." (PMID 36079985, 2022). "CEACAM-6 is overexpressed in multiple tumor types, including breast cancer and pancreatic cancer." (PMID 35804808, 2022). "While a number of PTVs were detected in these genes, two splicing mutations, CEACAM6 c.∗40 + 2T > G and CEACAM8 c.∗40 + 2T > G, were individually determined to be associated with European American breast cancer, both of which affect non-coding exons in the 3′ UTR." (PMID 34447411, 2021). "It has also been demonstrated that CEACAM5, CEACAM6, and CEACAM19 are overexpressed in breast cancer and are associated with enhanced tumor invasiveness and metastasis." (PMID 34447411, 2021). "Considering that CEACAM6/8 co-expression inhibits proliferation and invasiveness of breast cancer cells, having a rare PTV in one of those two genes may be sufficient to override their synergistic tumor-suppressing relationship." (PMID 34447411, 2021). "In a previous study, we have evaluated CEACAM6-expression in breast carcinomas." (PMID 33196697, 2020). "CEACAM6 is also overexpressed in breast cancer, and its expression in atypical ductal hyperplasia may be a biomarker for the invasiveness of breast cancer." (PMID 29137373, 2017). "We observed a variable expression of CEACAM6 in hepatocellular carcinomas (35 %), squamous cell carcinomas of the lung (60 %), renal cell carcinomas (14 %), urothelial carcinomas (13 %), serous carcinomas of the ovary (17 %), and breast carcinomas (11 %)." (PMID 25427744, 2015). "Hence, our findings that down regulation of CEACAM6 by siRNA led to the loss of the viability of BT474 and SKBR3 cells are novel and demonstrate an oncogenic role for CEACAM6 in breast cancer." (PMID 23592399, 2013). "Gene expression data from the microarray analysis of 92 primary breast tumors (from the UNC Microarray Database) were analyzed for expression of the six genes (CEACAM6, CDH1, CST6, ESR1, LCN2, and SCNN1A) whose loss characterizes the hypermethylator phenotype among breast cancer cell lines." (PMID 18221536, 2008). "This indicates that relatively lower CEACAM6 expression levels before chemotherapy are associated with achieving pCR following NAC, supporting its potential as both a predictive and therapeutic biomarker for the efficacy of neoadjuvant treatment in breast cancer." (PMID 40936892, 2025). "Interestingly, in breast cancer, CEACAM6 status has been shown to be higher in both ER-positive tamoxifen-resistant breast cancer and HER-positive trastuzumab-resistant breast cancer than in treatment-responsive disease, suggesting CEACAM6 as a potential target for the subsequent lines of therapy." (PMID 38279989, 2024). "NEO-201 is an IgG1 humanized mAb that binds specifically to tumor-associated variants of CEACAM-5 and CEACAM-6 expressed by colon, ovarian, pancreatic, non-small cell lung, head and neck, cervical, uterine and breast cancers, but is not reactive against most normal tissues." (PMID 35804808, 2022).
breast carcinoma (continued). "Moreover, the fact that 93% of CEACAM5-positive breast carcinomas in this study also express CEACAM6 suggests that multiple CEACAMs may act in concert, further complicating the consequences of CEACAM5-expression." (PMID 33196697, 2020). "Therefore, CEACAM5 and CEACAM6 may be promising targets for cancer immunotherapy including, perhaps, immunotherapy aimed at targeting breast cancer stem cells and metastatic disease." (PMID 23285151, 2012). "The results demonstrated that the expression levels of OLR1, ADIPOR1, CEACAM6, DNASE2, CD53, BMF, and CAMP were significantly elevated in breast cancer samples compared to healthy controls (p < 0.05)." (PMID 40282270, 2025). "These efforts provide translational evidence to support CEACAM6 as a predictive biomarker and potential therapeutic target in the NAC setting for HR+/HER2− breast cancer." (PMID 40936892, 2025). "Residues in CEACAM6 and CEACAM8 have been identified that are critical for CEACAM6 homodimerization as well as the formation of CEACAM6 and CEACAM8 heterodimers, which is important in preventing breast cancer cell proliferation." (PMID 34447411, 2021). "Conversely, CEACAM6 and CEACAM8 co-expression inhibits proliferation and invasiveness of breast cancer cells." (PMID 34447411, 2021). "To corroborate these immunohistochemical staining results, we performed western blotting on breast cancer cell extracts, and confirmed the specificity of CB30 and COL-1 for CEACAM5 as well as the cross-reactivity of 1105 with CEACAM6." (PMID 33196697, 2020). "Up-regulated expression of COL10A1, MMP11, CST1, GJB2, MMP1, MMP13, and CEACAM6; down-regulated expression of ADH1B, CIDEC, THRSP, GPD1, TIMP4, FABP4, and SCARA5 genes was common in breast cancers of the two populations." (PMID 31292488, 2019). "Marker Cluster 4 genes are enriched in HER2-positive breast cancers and includes ERBB2 (HER2), GRB7 and CEACAM6." (PMID 30279965, 2018). "Expression of TBC1D9 and CEACAM6 was higher in GATA3 mutant MCF-7 cells, GATA3 mutant CAMA1 cells, and primary GATA3 mutant breast cancer cells, whereas expression of PPT1, CYBRD1, HOXC13, and AFF3 was higher in GATA3 wild type cells." (PMID 29262572, 2017). "Targeting CEACAM6 with monoclonal antibodies has shown potential in reversing immune suppression in preclinical studies, supporting its relevance as a therapeutic target in HR+/HER2− breast cancer." (PMID 40936892, 2025). "Although we did not directly evaluate ESR1 or PI3K/AKT gene alterations, incorporating CEACAM6 into multi-marker predictive models may enhance patient stratification and inform more personalized therapeutic approaches in HR+/HER2− breast cancer." (PMID 40936892, 2025). "Interestingly, CEACAM5 and CEACAM6 facilitates metastatic progression of breast cancer, and CDH family is also known for their oncogenic role in several cancers including breast cancer." (PMID 40420099, 2025). "In previous studies, we demonstrated that NEO-201 reacts to colon, ovarian, pancreatic, non-small cell lung, head and neck, cervical, uterine and breast cancers expressing tumor-associated variants of CEACAM5 and CEACAM6 but does not react to normal tissues." (PMID 36291783, 2022). "Since the role of CEACAM6 in human breast cancer and in particular in relation to PDEF remains poorly understood, this communication also describes the characteristics of PDEF and CEACAM6 expression in primary breast tumors and their contributions to the tumor phenotype." (PMID 23592399, 2013). "The results presented in this study also suggest high promise of targeting PDEF and CEACAM6 in breast cancer, independent of and/or in conjunction with the existing ER and Her2 targeted treatments of hormone receptor-positive and Her2 over expressing tumors." (PMID 23592399, 2013). "Integrating CEACAM6 into predictive frameworks alongside immune and pathway features may enhance individualized treatment strategies and improve clinical outcomes in HR+/HER2− breast cancer." (PMID 40936892, 2025).
breast carcinoma (continued). "In addition, we retrospectively analyzed a clinical cohort of 106 HR+/HER2− breast cancer patients receiving NAC and performed paired immunohistochemical (IHC) validation of CEACAM6 expression before and after treatment to examine its correlation with pCR status." (PMID 40936892, 2025). "TGF-β or EGF on HER2-overexpressed breast cancer cells can induce SMAD3 phosphorylation, and CEACAM6 expression level is upregulated after treatment, but this correlation is not obvious in HER2-negative breast cancer cells." (PMID 38796667, 2024). "Pyllodes breast cancer is a stromal tumor, usually benign, and should therefore not express CEACAM5 or CEACAM6." (PMID 17201906, 2007).
colorectal cancer (32 papers, 2005 to 2025). A primary or metastatic malignant neoplasm that affects the colon or rectum. "Among these, “cancer” and “colorectal cancer” were found in more than 50 CEACAM6-associated articles (202 and 65, respectively, as of March 2022)." (PMID 39239252, 2022). "In contrast, expression of CEACAM6 in colorectal cancer tissue is significantly associated with poor prognosis." (PMID 25427744, 2015). "In summary, we identified CEACAM6 as a biomarker for acid-resistant clones in colorectal cancer, induced further by acidity, and highly expressed in later-stage disease." (PMID 38502695, 2024). "Using GMM, we showed that CEACAM5 and CEACAM6 mRNA levels in the panel of 68 colorectal cancer cell lines were bimodally distributed." (PMID 38502695, 2024). "Other studies identified that CEACAM6 was a factor of independent prognostic significance in colorectal cancer and gastric cancer." (PMID 37249822, 2023). "To evaluated the effect of pHLIP-miR-29a in other than lung cancer, we selected colorectal cancer, which is known for its typical expression of CEACAM6." (PMID 37684602, 2023). "In colorectal cancer, CEACAM6 overexpression independently predicted poor OS and disease-free survival, whereas CEA was not significantly related to these outcomes." (PMID 28883649, 2017). "Tissue expression of CEACAM6 in liver metastases of colorectal cancer is higher than that in primary colorectal cancer." (PMID 25427744, 2015). "CEACAM6 overexpression has been identified as an independent predictor of poor overall survival in colorectal cancer patients." (PMID 25938545, 2015). "To date, pancreatic and colorectal cancers have been the primary focus of CEACAM6 expression studies." (PMID 25427744, 2015). "Upregulation of CEACAM6 expression in hyperplastic polyps and early adenomas indicates that it is an early event in the development of colorectal cancer." (PMID 25427744, 2015). "CEACAM6 expression in colorectal cancer inversely correlates with cellular differentiation and is an independent prognostic factor associated with a higher risk of colorectal cancer relapse." (PMID 25427744, 2015). "Before we analyzed the relationship between IL-6 and CEACAMs, we examined the expression of CEACAM5 and CEACAM6 in the normal mucosa-derived and colorectal cancer cell lines." (PMID 26673628, 2015). "Previous results showed that CEACAM6 attenuation increased E-cadherin promoter activity in colorectal cancer." (PMID 25398131, 2014). "By 3 months of age, the expression level and pattern of CEA/CEACAM6 in the CEABAC20 mice were similar to those of human colorectal carcinomas." (PMID 18159236, 2007). "As an approximate estimate, immunohistochemistry for CEA/CEACAM6 was performed on colonic sections from 3 week and 3 month old transgenic mice and compared with that of human colorectal carcinomas at a common stage of progression." (PMID 18159236, 2007). "CEACAM6 overexpression independently predicts poor overall and disease-free survival, and correlates inversely with cellular differentiation in colorectal cancer." (PMID 16868542, 2006). "Thus, CEACAM6 is a marker of acid-resistant clones in colorectal cancer and a potential motif for targeting therapies to acidic regions within the tumors." (PMID 38502695, 2024). "Finally, CEACAM6 levels were strongly increased in human colorectal cancers from stage II and III patients, compared to matched samples from adjacent normal tissues." (PMID 38502695, 2024). "CEACAM6 has been found to be highly expressed in various common cancers, including colorectal cancer, pancreatic duct adenocarcinoma (PDAC), intrahepatic cholangiocarcinoma, gastric cancer (GC), non-small cell lung cancer (NSCLC), and head and neck squamous cell adenocarcinoma (HNSCC)." (PMID 38796667, 2024).
colorectal cancer (continued). "Furthermore, ALDOB‐mediated lactate production increases carcinoembryonic antigen‐related cell adhesion molecule 6 (CEACAM6) protein stability by inducing Kla, which promotes cell proliferation and 5‐FU chemoresistance in colorectal cancer (CRC) cells." (PMID 39417674, 2024). "Taken together, these results indicate that CEACAM6 is involved in an acid- or hypoxia-triggered stress response in colorectal cancer cells but is not linked to HIF1α signaling or under control by CDX1/2." (PMID 38502695, 2024). "However, both tumor and normal-tissue-derived organoids in culture highly expressed CEACAM6, verifying that normal-tissue-derived organoids acquired some gene expression features of colorectal cancer cells." (PMID 35484598, 2022). "As CEACAM6 has universal oncogenic features, it has been reported as a relevant prognostic biomarker in other malignancies: cholangiocarcinoma, osteosarcoma, renal cancer, colorectal cancer, gastric cancer." (PMID 34207784, 2021). "Thus, the aim of this study was to systematically analyze the impact of IL-6 classic and trans-signaling on the expression of CEACAM5 and CEACAM6 in colorectal cancer cells." (PMID 26673628, 2015). "However, CD66c/CEACAM6 was reported to be a marker of colorectal cancer stem cells and was also shown to be heterogeneously expressed in cultured human large airway basal cells by confocal microscopy." (PMID 25551685, 2014). "Previous studies indeed demonstrated that CEACAM6 is a novel marker for colorectal cancer stem cells and may serve as a potential therapeutic target for pancreatic adenocarcinoma." (PMID 24423398, 2013). "In various cancers such as PDAC, GC, colorectal cancer (CRC), cholangiocarcinoma (CCA), and osteosarcoma, CEACAM6 has been found to be involved in EMT regulation, tumor invasion, and metastasis." (PMID 38796667, 2024). "As expected, tumor-derived organoids highly expressed in vivo tumor-specific genes, many of which have been widely reported to be closely related to colorectal cancer progression and metastasis, such as PROCR, SCD, BMP4, CEACAM6, TESC, and TGFBI." (PMID 35484598, 2022). "Genes elevated in colorectal cancer metastasis included higher expression of Cadherin 17 (CDH17) and the adhesion molecules CEACAM5 and CEACAM6, previously shown to correlate with metastasis colonization." (PMID 33332768, 2020). "We confirmed this finding at the protein level in the two normal mucosa-derived cell lines (CSC1, NCM460) and two representative colorectal cancer cell lines which express CEACAM5 and CEACAM6 (HT29p, HT29c)." (PMID 26673628, 2015). "If these results can be extrapolated to human colorectal cancer, in which up-regulation of CEA and CEACAM6 occurs as an early event in adult colonic epithelium, the magnitude of the tumorigenic effects observed here would imply a very significant contribution to the malignant phenotype." (PMID 18159236, 2007). "Indeed, studies from colorectal cancer models have shown that CEACAM6 mediates inhibition of T-cell activation that is not redundant with the PD-1/PD-L1 axis." (PMID 38279989, 2024).